IL6 (interleukin 6)
Diseases named in the same sentence as IL6 in open-access papers (continued):
Sharing a sentence is not in itself a finding about the gene and the disease.
tumor (continued). "The dose–response analysis of low-affinity FolR1-TCB targeting high- and low-expression cells showed that there was only minimal tumor lysis and no IL6 release in the low-expression cell line, suggesting that low-expression tissues would be minimally targeted by the low-affinity variant." (PMID 34862519, 2021). "In addition, the TBK1 antagonist resulted in the decreased level of α-SMA+ myofibroblasts in non-tumor liver tissues and IL-6 in tumor tissues demonstrated by IHC staining and ELISA." (PMID 33679751, 2021). "However, certain cytokines, such as tumor necrosis factor-α (TNF-α), and interleukin-6 (IL-6), can be also induced by tumor cells as well as non-cancerous cell types, such as epithelial cells or cancer-associated fibroblasts (CAFs)." (PMID 34557865, 2021). "Furthermore, ginsenoside Rg3 could stimulate tumor cells to produce IFN-γ, an anti-tumor cytokine secreted by T cells, while suppressing tumor cell secretion of TGF-β and IL-6." (PMID 35002732, 2021). "IL-6 is the major cytokine that stimulates proliferation of tumor cells, and it inhibits apoptosis via activation of the STAT3 signaling pathway 18 TNF-α could activate NF-κB and AKT signaling cascades and stimulate tumor progression." (PMID 33391471, 2021). "In addition to promoting the infiltration of immune cells into the tumor, IL-6 has also been reported to enhance STAT3 phosphorylation, which increases anti-apoptosis of tumor cells; specifically, overexpressed IL-6 has been identified as a marker of malignancy in GBM." (PMID 34337348, 2021). "Finally, we confirm the importance of MyD88 in macrophages showing that BCG induces the release of inflammatory cytokines (TNF-α, IL-6, IL-1β) and nitric oxide by WT macrophages in co-culture with infected tumor cells, but not in MyD88−/− BMDMs." (PMID 34341449, 2021). "In addition, IL-6 is a potent activator of signal transducers and activators of the transcription (STAT) factors STAT1 and STAT3, which play an important role in the progression of neoplasia." (PMID 33922946, 2021). "Under the influence of tumor-derived cytokine and growth factors [e.g., VEGF, granulocyte macrophage colony stimulating factor (GM-CSF), macrophage colony-stimulating factor (M-CSF), TGF-β, IL-4, IL-6, and IL-10], MDSCs acquire inhibitory activity against various anti-tumor immune cells." (PMID 34988072, 2021). "Moreover, the linear regression analysis between lg baseline PET/CT metabolic parameters and lg (peak IL-6), lg (peak IFN-γ), and lg (peak ferritin) exhibited a positive correlation between baseline tumor metabolic burden and serum cytokine concentration during CRS occurrence." (PMID 34422666, 2021). "Moreover, M2 macrophage also releases cytokines and chemokines, such as IL-6, TNFα, and CCL22, activates TGF-β signaling pathway, and promotes angiogenesis and epithelial–mesenchymal transition, thereby facilitating tumor progression." (PMID 35047494, 2021). "Namely, there are a host of differentially expressed proteins when cells are treated with lobaplatin compared to control tumor cells, while no more than 100 proteins were differentially expressed between cells treated with lobaplatin and those pretreated with IL-6 before lobaplatin treatment." (PMID 33791202, 2021). "Here, we show that IL-6 and HGF, secreted by tumor neighboring visceral adipose stromal cells (V-ASCs), expand the metastatic colorectal (CR) cancer cell compartment (CD44v6 + ), which in turn secretes neurotrophins such as NGF and NT-3, and recruits adipose stem cells within tumor mass." (PMID 34408135, 2021). "Further, increased IL-6 levels after TKI treatment and subsequent inhibition of the IL-6 signaling pathway enhanced efficacy of sorafenib, another TKI that blocks VEGF and PDGF receptors, which is approved for advanced RCC on suppressing angiogenesis and tumor growth." (PMID 34931665, 2021).
tumor (continued). "In addition, Lack of interleukin-6 in the tumor microenvironment augments type-1 immunity and increases the efficacy of anti-PD-L1 therapy in CT26 cells mouse model." (PMID 34479503, 2021). "Despite the fact that different cellular sources are being used for CAF-tumour in vitro studies, some common pathways are being described for CAFs in primary and secondary cancers such as the involvement of pro-fibrogenic growth factor TGF-β and inflammatory cytokine IL-6." (PMID 34885024, 2021). "Importantly, some of the cytokines and chemokines upregulated in the tumor were also elevated in the plasma of mice receiving heterologous KV vaccine, including increased levels of IFN-γ, CCL5, CXCL10, CCL2, IL-6, CXCL1, and IL-1β one day after VSV-GP-HPV boost." (PMID 34465781, 2021). "Dendritic cells loaded with TEXs in tumor-draining lymph nodes could promote the production of pro-inflammatory cytokines, then the level of IL-6, IFN-γ and IL-12 in the tumor microenvironment would become high, while the IL-10 was of a low level, which promoted the anti-tumor response of Th1." (PMID 33922480, 2021). "In the presence of conditioned medium from RMG-1 cells transfected with siAng1 and treated with anti-IL-6 antibody, Bev reduced the tube area by 55%, similar to the findings in assays using conditioned medium from tumor cells that were not treated with anti-IL-6." (PMID 33833265, 2021). "Strikingly, macrophage depletion not only elicited an immune activated TME to attenuate tumor growth but also reduced the tumor-infiltrating PD-1+CD8+ T cells, suggesting that PD-1 expression on CD8+ T cells may be stimulated by the IL-6 produced by macrophages." (PMID 34093869, 2021). "Necrosed tumor cells may contribute to an inflamed TME and also proinflammatory cytokines released by CSCs, such as IL-6, IL-8, IL-10, and IL-13 can contribute to maintaining an inflammatory and suppressive TME representing the “niche” sustaining cellular stemness." (PMID 33494389, 2021). "Tumor-derived IL-6 and CSF-1 affect DC differentiation, promoting lineage commitment toward suppressive monocytes and VEGF inhibits DC maturation by suppressing NFκB signaling in hematopoietic progenitors as well as the tumor-derived TGF-β can inhibit antigen uptake." (PMID 33418996, 2021). "Moreover, considering the elevation of FOXP3, IL-6, and IL-17 levels in these cells, exosomes secreted by CML cells may induce the fates of T cells toward tumor favorable T cells instead of conventional activated T cells." (PMID 34493241, 2021). "Another study showed that Palbociclib treatment led to the downregulation of the DNA repair pathway and the upregulation of IL-6/STAT3 pathway, and the combination using STAT3, PARP andCDK4/6 inhibitors could target these pathways and greatly inhibit tumour growth." (PMID 33832512, 2021). "We analyzed a variety of clinical factors that may be associated with CRS (gender, age, transplantation, CAR-T cell dose, bone marrow tumor burden, species of CAR, costimulatory molecules, serum maximum values of IL-6 and CRP, and minimum level of CD4/CD8) separately." (PMID 33708205, 2021). "Some studies have also shown, that IL6 signaling can lead to STAT3 activation, further by promoting expression of vascular endothelial growth factor (VEGF) and fibroblast growth factor (bFGF) by tumor cells, supporting the rapid vascularization within tumor tissues." (PMID 34445494, 2021). "In our study, we found after co-culture with Treg, only tumor cell U251 produced IL6, which suggested that tocilizumab may directly act on tumor cells, not on Tregs." (PMID 33576874, 2021). "Moreover, considering the elevated FOXP3, IL-6, and IL-17 levels in these cells, CML cell-derived exosomes may induce T cell fate toward tumor favorable T cells instead of conventional activated T cells (Th1, Th2, CTL, etc.)." (PMID 34493241, 2021).
tumor (continued). "Although pre-clinical studies have produced diverging evidence on the effects of IL6 and the utility of its in-tumour levels as a marker remains unclear, the role of circulating serum IL6 levels as a negative prognosticator in BC has been well established." (PMID 34834425, 2021). "As interleukin (IL-6) levels were significantly higher in pre-radiotherapy serum and tumor tissues of non-responders, overexpression of IL-6 may be signal a poorer prognosis." (PMID 34988334, 2021). "Additionally, IL-6 induces the production and maintenance of BC stem cells through the activation of nuclear factor kappa-light-chain-enhancer of activated B cells (NF-kB) and STAT3, thereby promoting tumor progression." (PMID 34638283, 2021). "Moreover, the most undifferentiated stem-like PC cells expressed the highest levels of IL-6 and IL-6R: blockade of JAK/STAT3 signaling could inhibit colony-forming and tumor initiation." (PMID 34830209, 2021). "Furthermore, Hsiao and colleagues determined that exogenous combination IFN-γ and IL-6 therapy could increase the expression of MHC class I and II molecules on tumor cells, potentially enhancing the ability of T cells to recognize and target cancer cells." (PMID 34504657, 2021). "TAFs interact with stromal cells by secreting growth factors, cytokines, and chemokines, including IL6, TGFβ, and CCL2, to amplify immune evasion systems, attracting immunosuppressive cells into the tumor microenvironment, and they also form a network of proinflammatory mediators at the tumor site." (PMID 33384409, 2021). "It is important to point out that particular cytokines, including IL-6, IL-17, and IL-23, are capable of either promoting or inhibiting cancer cell proliferation, as well as others, including IL-12, TRAIL, and IFN-γ, in contributing to the development and progression of a tumor." (PMID 34502312, 2021). "The median serum levels of AFP, PIVKA-II, GPC-3, adiponectin and IL-6 were significantly higher in patients with HCC compared to those without tumor (all p < 0.001); only the plasma leptin values were not different between the two groups of patients (p = 0.649)." (PMID 34064999, 2021). "Therefore, EGCG impaired tumor growth in a murine model of breast cancer by both decreasing TAM tumor infiltration and repolarizing M2-like to M1-like macrophages, as evidenced by the diminished IL-6 and TGF-β and increased TNF-α levels." (PMID 33572626, 2021). "However, the limitation of our preliminary work is that the relationship between tumor-derived IL-6 and macrophage MMP12 has not been well explored." (PMID 34863141, 2021). "We also investigated whether BLT2 inhibition could suppress tumor formation and IL-6 production in these mice and observed that treatment with LY255283 clearly suppressed KRAS-driven lung tumor formation and IL-6 production." (PMID 34635780, 2021). "Cytokines such as IL-6, IL-8, and IL-2 were found to be up-regulated as well in culture supernatants of MCF-7 following treatment with zerumbone and paclitaxel, this will further contribute to promoting inflammation that will eventually activate the host immune response against tumor." (PMID 35317109, 2021). "Furthermore, MSCs secrete cytokines like angiopoietin-1 (Ang-1) and IL-6 in colorectal carcinoma, in turn stimulating cancer cells to secrete endothelin-1 (ET-1), which in turn activates ERK and AKT paths in tumor endothelial cells, resulting in tumor vessel formation and mobilization." (PMID 33472580, 2021). "In addition, the anti-tumor effects of JAK2/3 inhibitor AG490 was observed in WT mice but not in Rab37 KO mice, consistent with the hypothesis of Rab37/IL-6/STAT3/PD-1 functioning in the same axis." (PMID 34093869, 2021). "In addition to fibroblast-derived IL-6, we verify that exogenous IL-6 induces CRC cell invasion via IL-6R, consistent with previous study that anti-IL-6R antibody suppresses angiogenesis and inhibits the interaction between tumor and stroma." (PMID 32855767, 2020).
tumor (continued). "A study in 2011 revealed that IL-6 is essential in converting non-stem cancer cells to CSCs in human prostate and breast cell lines, and that CSCs express and release naturally higher levels of IL-6 than their non-stem counterparts, thus promoting tumor aggressiveness." (PMID 32790767, 2020). "However, direct co-culturing of LS1034 cells with fibroblasts was much more effective in inducing tumor cell surface CD44 indicating that IL-6 is not the central in this scenario." (PMID 32685007, 2020). "Furthermore, growth factor inhibitors such as IL-6 inhibitors (tocilizumab) and MMP-2/-9 inhibitors (β-d mannuronic acid) have been designed to affect tumor progression, invasion, and metastasis by inhibition of chronic immune response and prevention of remodeling ECM." (PMID 32370233, 2020). "Analysis of the xenografts by using mouse and human ELISA revealed that only human IL-6 and IL-8 could be detected, thus suggesting that their source is tumour derived, rather than being from the endogenous mouse microenvironment." (PMID 31772325, 2020). "AMPK suppresses tumor survival through inhibition of mTOR by increasing the expression of p-TSC2, a tumor suppressor gene, and leads to the inactivation of AKT and lipopolysaccharide (LPS)-induced IL-6/JAK2/STAT3 signaling in triple-negative breast cancer (TNBC)." (PMID 31952344, 2020). "It is well-established that pro-inflammatory cytokines, such as IL-6 and IL-8, play crucial roles in the generation and maintenance of the stem cell-like fraction in tumor cells through stimulating NF-κB and STAT3 signaling, which promotes therapy resistance, tumor recurrence, and metastasis." (PMID 32244804, 2020). "These cells establish a favorable environment for tumor development by releasing cytokines (IL-6, IL-10 and TGF-β), metalloproteinases (MMP3 and MMP9) and growth factors (HGF, EGF, CTGF and IGF-1), leading to immunomodulation, angiogenesis, invasion, proliferation and tumor cell survival." (PMID 32899449, 2020). "Furthermore, NK cells, like CD8+ T cells, act against the tumour by inducing pro-apoptotic and pro-inflammatory factors such as TNF-α, IL-6, IFN-γ and granulocyte-macrophage colony-stimulating factor (GM-CSF) in an attempt to induce proliferation and differentiation of hematopoietic cells." (PMID 33371214, 2020). "It was reported that CAFs influenced the tumor growth and progression, especially invasion and metastasis, via the secretion of many kinds of cytokines such as vascular endothelial growth factor A (VEGFA), CXCL12, Interleukin 6 (IL-6), and the physical remodeling of the ECM." (PMID 32377504, 2020). "For instance, IL-6, IL-17, and IL-11 may increase the proliferation of tumor cells, under conditions, such as chronic hypoxia, lack of nutrients, or insufficiency of anti-tumor immunity." (PMID 32973519, 2020). "Of interest was the fact that tumor cell-expressed CD90 was required for generating physical contacts between the tumor cells and macrophages, and these interactions have increased the expression of IL-6, CXCL8 and granulocyte-macrophage colony stimulation factor (GM-CSF) in the cancer cells." (PMID 33585241, 2020). "Moreover, TGF-β in the tumor microenvironment triggers the expression of TIM-3 on the surface of TAMs and subsequent IL-6 secretion; the TAM-derived IL-6 further activates the IL-6/signal transducer and activators of transcription (STAT3) pathway in the tumor, sustaining survival and proliferation." (PMID 32722054, 2020). "This led to focus on the possible anti-tumor effect of TU-100 to cancel the interaction between HSCs and tumor cells, and present studies have shown that TU-100 has inhibited HSC activation promoted by cancer cells, and suppressed the secretion of IL-6 in HSCs." (PMID 33346211, 2020).
tumor (continued). "Nevertheless, the findings from this experiment indicated a decrease in p-STAT3 after siltuximab treatment, and the researchers speculated that siltuximab had no clinical effect possibly because of tumour autocrine IL-6 and tumour heterogeneity." (PMID 32760201, 2020). "The bone marrow-derived multipotent mesenchymal stromal cells, under the influence of interleukin-6 (IL6) and chemokine (C-X-C motif) ligand-7 (CXCL7; also known as the pro-platelet basic protein), reportedly are capable of enriching the population of BCSCs in the tumor." (PMID 32883003, 2020). "Since IL-6/STAT3/IL-10/TGF-β plays pivotal role in carcinogenesis and EMT39–43,45–48, to verify whether this axis is involved in malignant transformation of tumor cells regulated by transformed macrophage-CMs, we detected the changes of several major indicators in this process." (PMID 33288772, 2020). "Our findings in this study corroborated the tumor-suppressive roles of miR-142-3p, in that transfection of CRC cells with miR-142-3p mimic molecules resulted in decreased expressions of LGR5, β-catenin, mTOR, and IL-6 as well as reduced SPs, as a surrogate of reduced ABCG2 expression." (PMID 32560222, 2020). "Similarly, another study found that tumor cell debris, after cancer therapy, promotes survival and growth of living cancer cells in multiple tumors through the secretion of pro-inflammatory cytokines such as TNF-α, IL-6, IL-8, CCL4, and CCL5 by macrophages." (PMID 32326073, 2020). "While our results do not rule out inhibitory roles for tumor-expressed IL-6 on CD103+ cDC1 function, we anticipate CD103+ cDC1s are refractory to tumor-derived LIF or G-CSF due to the relatively low abundance of receptor mRNAs in this subset relative to other immune populations." (PMID 31947933, 2020). "The increased serum IL-6 activated STAT3/c-MYC signaling in peripheral monocytes, enhanced the transcription of miR-25–3 p, suppressed PTPRO expression, promoted PD-L1 through both JAK2/STAT3/c-MYC and JAK2/STAT1 signaling, and promoted tumor growth by enhancing T-cell exhaustion." (PMID 32581055, 2020). "By combining these findings, we could anticipate that I-MDSCs in CRC microenvironment are activated and recruited to tumor sites where they differentiate into mature phenotypes and become immune suppressive under the influence of MAPK- and IL-6-mediated signaling pathways." (PMID 31941522, 2020). "In the current study, the secretion of interleukin-6 (IL-6), granulocyte colony-stimulating factor (GCSF) and chemokine (C-X-C motif) ligand 16 (CXCL16) was increased by the STK24-knockdown tumor cells in comparison to the secretion by the control-pEGFP tumor cells." (PMID 31892988, 2020). "Although we did not investigate these factors, tumor circumstance and cells may have affected the IL-6 pathway." (PMID 32138303, 2020). "The tumour microenvironment (TME) is an inflammatory environment, containing various inflammatory and regulatory mediators such as cytokines (tumour necrosis factor (TNF), Interleukin (IL)-1β, IL-6 and IL-10), as well as chemokines and reactive oxygen species (ROS)." (PMID 32183059, 2020). "Furthermore, MSCC WT keratinocytes showed an increased expression of CCN2 when the conditions that occur during DMBA/TPA treatment were mimicked by application of either TPA or IL-6, the cytokine up-regulated during DMBA/TPA tumorigenesis and crucial for tumor formation." (PMID 32423907, 2020). "Neutrophilia provide a favorable tumor microenvironment for cancer progression by secreting many inflammation mediators such as tumor necrosis factor alpha (TNF-α), vascular endothelia growth factor (VEGF), interleukin-2 (IL-2), interleukin-6 (IL-6), and interleukin-10 (IL-10)." (PMID 32911724, 2020).